TNF (tumor necrosis factor)
Diseases named in the same sentence as TNF in open-access papers (continued):
Sharing a sentence is not in itself a finding about the gene and the disease.
osteoporosis (continued). "By contrast, the bone mineral density of the whole body was correlated with RANKL-induced osteoclasts, but not with TNF- or IL-6-induced osteoclasts, indicating that “inflammatory cytokine-generated osteoclasts” may contribute to the pathology of RA but not to whole-body osteoporosis." (PMID 36172385, 2022). "Expression levels of ALPL, BGLAP, and TNF were not significantly different between control and osteoporosis groups, but those of ACP5 and CTSK were significantly increased in patients with osteoporosis compared to those in the controls." (PMID 37339951, 2023).
prostate carcinoma (401 papers, 2003 to 2025). A carcinoma that arises from epithelial cells of the prostate gland. "In models of prostate cancer, lycopene treatment induces a decrease in the concentration of inflammatory mediators such as TNF-α, IL-1β, IL-6, IL-8, IL-10, and TGF-β associated with a reduction in tumor growth and an increase in survival." (PMID 40420174, 2025). "CNP and prostate carcinoma patients are associated with prolonged overproduction of inflammatory cytokines, including IL‐1β, IL‐6, and TNF‐α." (PMID 40552335, 2025). "Interruption of Klf5 acetylation in Pten-deficient prostate cancer cells signaled iCAFs through TNF-α to promote FGF9 release, which in turn activated FGFR1 signaling in prostate cancer cells." (PMID 38781024, 2024). "The modulation of the p38 MAPK/JNK pathway has also been implicated in the antagonistic mechanism of a TNF-α-derived nanodrug against prostate cancer, which promotes caspase-dependent apoptosis." (PMID 38727308, 2024). "A different study found that TNF-A -1031C-863C-857T-308G and TNF-α-1031 CC genotype and the haplotype expressions were associated with a higher risk of prostate cancer." (PMID 39554609, 2024). "High levels of TNF expression in tumor tissues are associated with malignancy progression, too, and have been reported in chronic lymphocytic leukemia, prostate cancer, and other cancer types." (PMID 36289890, 2022). "Our meta-analysis aimed to estimate the association between TNF-α rs1800629 (− 308 G/A), rs361525 (− 238 G/A) and rs1799724 polymorphisms and prostate cancer risk." (PMID 32264962, 2020). "Several studies have focused on the association between TNF-α polymorphisms and prostate cancer development." (PMID 32264962, 2020). "While IL-6 derived from macrophages and adipocytes has pro-inflammatory effects, muscle-derived IL-6 can counteract TNF-α, which as previously discussed, is associated with significantly worse outcomes in men with prostate cancer." (PMID 32056047, 2020). "Eligible studies were identified from electronic databases (PubMed, Embase, Wanfang and CNKI) using keywords: TNF-α, polymorphism, prostate cancer, until Nov 15, 2019." (PMID 32264962, 2020). "Expression of tumor necrosis factor-α (TNFα) in the serum of prostate cancer patients is associated with poorer outcome and progression to castrate-resistant (CRPC) disease." (PMID 30349042, 2018). "We have previously demonstrated that BA causes apoptosis in androgen-refractory PC-3 human prostate cancer cells, and sensitizes these cells to TNFα-induced apoptosis through suppression of NF-κB." (PMID 28208611, 2017). "TNFα, despite its name, has many pro-tumour actions, and high tumour levels of this cytokine are associated with a poor prognosis in prostate cancer." (PMID 28910408, 2017). "In concordance to our observation, high serum TNF-α level has been associated with poor prognosis having reduced survival in prostate cancer and epithelial ovarian cancer." (PMID 26881177, 2016). "MetS features are known to accompany a pro-inflammatory state (elevated levels of C-reactive protein, TNF-α, interleukin 8, 6, 1β), which in turn has been related to prostate cancer risk." (PMID 27386844, 2016). "With respect to TNF-α-308G/A polymorphism, 14 studies including 5,757 prostate cancer cases and 6,137 controls were found in our meta-analysis." (PMID 24666463, 2014). "Our meta-analysis summarized for the first time all the available data on the association between TNF-α-238G/A polymorphism and prostate cancer risk, including a total of five studies, involving 1,967 prostate cancer cases and 2,004 controls." (PMID 24666463, 2014). "Data from five case–control studies comprising 1,967 prostate cancer cases and 2,004 controls were pooled for the analysis of the TNF-α-238G/A polymorphism." (PMID 24666463, 2014). "Two common polymorphisms in the TNF-α gene, −308G/A and −238C/T, have been suggested to alter the risk for prostate cancer, but the results have been inconclusive so far." (PMID 24666463, 2014).
prostate carcinoma (continued). "Similar to the total population, inheritance of sequence variants in IL1R2, IL10RA and TNF among U.S. men were linked with a significant increase in prostate cancer risk." (PMID 24359571, 2013). "In the total population, inheritance of the IL1R2 rs11886877 AA, IL8RB rs11574752 AA, TNF rs1800629 GA + AA, and TNF rs673 GA genotypes modestly increased prostate cancer risk by 1.45 to 11.7-fold relative to the referent genotype." (PMID 24359571, 2013). "A polymorphism in the TNF-α promoter resulting in enhanced plasma TNF-α has been associated with an increased incidence of prostate cancer, while a polymorphism increasing IL-1β production conferred a greater susceptibility to gastric cancer." (PMID 17367517, 2007). "Notably, TNF-α levels in prostate cancer are associated with disease severity and significantly increase during the metastatic phase." (PMID 40141200, 2025). "Additionally, other cytokines such as TNF-α, IL-8, and IL-1β have also been found to be associated with the development and progression of prostate cancer." (PMID 38833027, 2024). "The TNF-α-238, an allele, indicated a substantial risk for prostate cancer." (PMID 39554609, 2024). "Additionally, TNF-α is identified as a pivotal contributor to prostate cancer pathogenesis, closely associated with detrimental pathological characteristics of PCa." (PMID 39678517, 2024). "Similarly, higher levels of TNF-α are associated with more aggressive disease, prostate cancer progression, relapse and mortality." (PMID 32056047, 2020). "Although TNF has been associated with cell death in stimulated prostate cancer cells in vitro, an in vivo model using TNF receptor 1 knock-out mice suggests, rather, that TNF promotes prostate cancer proliferation." (PMID 30158439, 2018). "A significantly increased prostate cancer risk was found to be associated with the TNF-α-308C/T polymorphism in studies with healthy volunteers (AA + AG vs. GG: OR = 1.531, 95% CI = 1.093–2.145; P = 0.013; AG vs. GG: OR = 1.477, 95% CI = 1.047–2.085; P = 0.026)." (PMID 24666463, 2014). "Their results suggested that the TNF-α-308 G > A polymorphism might significantly contribute to prostate cancer susceptibility." (PMID 25420786, 2014). "As only five studies on the association between TNF-α-238G/A polymorphism and prostate cancer risk were included in our meta-analysis, meta-regression analysis and Galbraith plots analysis were not performed; therefore, these results require further investigation." (PMID 24666463, 2014). "Therefore, we performed a meta-analysis to comprehensively evaluate the association between TNF-α-308G/A and/or TNF-α-238G/A polymorphisms and prostate cancer risk." (PMID 24666463, 2014). "Inheritance of the TNF rs1800629 AA genotype was associated with a significant 1.8 fold increase in prostate cancer risk among Caucasian men in a small study (150 cases, 150 controls); however, this marker resulted in null findings in a larger study (468 cases, 468 controls)." (PMID 24359571, 2013). "Importantly, it was discovered that dNSurR9-C84A antagonizes survivin's ability to suppress TNF-α signaling, rendering prostate cancer cells susceptible to the proapoptotic effects of TNF-α." (PMID 20920299, 2010). "Similarly, a study with high-risk prostate cancer patients participating in physical exercise demonstrated improvements in fatigue along with a decrease in pro-inflammatory cytokines such as IL-1, IL-6, and TNF-α." (PMID 37507961, 2023). "Finally, the TNF-mediated vascular damage caused by ADT may provide an opportunity for prostate cancer therapy." (PMID 36551505, 2022). "Thus, it is biologically reasonable to hypothesize a potential relationship between TNF-α polymorphisms and prostate cancer risk." (PMID 24666463, 2014).
prostate carcinoma (continued). "Promoter polymorphisms in the TNF-α gene related to the pro- and anti-inflammatory response could directly influence production of TNF-α, thus causing inter-individual differences in immune responsiveness, which may influence the susceptibility of prostate cancer." (PMID 24666463, 2014). "The highest expression of TNF-α was observed in prostate cancer as compared to benign prostate hyperplasia." (PMID 39941741, 2025). "For example, in prostate cancer, TNF-α levels are positively correlated with disease severity and promote the growth and spread of various cancer cells, including those in the skin, ovary, pancreas, pleural cavity, and intestinal tract." (PMID 40360483, 2025). "In prostate cancer, C2Cnt induces apoptosis and prevents production of the pro-inflammatory cytokines TNF-α and interferon (IFN)-γ." (PMID 40290068, 2025). "It was also reported that knocking down endogenous MDK expression by siRNA enhanced TNF-α-induced apoptosis through activation of caspase-3 in prostatic cancer cells, and MDK had a protective role against cardiac ischemic/reperfusion injury." (PMID 40943439, 2025). "Previous studies showed that TNF-α presents of different actions in prostate cancer (pro- and anti-carcinogenic)." (PMID 39941741, 2025). "Research on prostate cancer has revealed that CA phenethyl ester can prevent NF-κB activation in prostate cancer-3 (PC-3) cells by preventing TNF-α and Paclitaxel from activating NF-κB." (PMID 40427522, 2025). "It has been reported that upregulation of NSD2 is correlated with increased expression of IL‐6 and TNF‐α via NF‐κB in prostate cancer." (PMID 38400589, 2025). "We have identified targets such as AKT1, TNF, IL6, STAT3, and CTNNB1 in Osthole’s inhibition of prostate cancer, along with pathways including the TNF signaling pathway, the Interleukin-6-17 (IL-6-17) signaling pathway, and the prolactin signaling pathway." (PMID 40978029, 2025). "Chronic inflammation in the tumor microenvironment can lead to increased cytokine production (e.g., IL-6, TNF-α, IL-1β), which promotes both prostate cancer progression and the survival/proliferation of abnormal plasma cell clones in MGUS." (PMID 41374992, 2025). "Silencing or inhibiting endogenous ANO1 has been demonstrated to suppress prostate cancer growth, induce apoptosis, and enhance TNF-α expression." (PMID 40356890, 2025). "By modulating key inflammatory mediators on the TNF/IL-17 axis, Lan C disrupts this pro-tumorigenic signaling, offering a novel approach for the treatment of prostate cancer." (PMID 40141200, 2025). "In this study, we aim to investigate the anticancer effects of Lan C in human prostate cancer cells, with a particular focus on its ability to modulate the TNF/IL-17 signaling pathway and induce apoptosis." (PMID 40141200, 2025). "In clinical studies, elevated TNFα levels have been found in the blood of patients with renal, pancreatic, breast, and prostate cancers, interestingly in correlation with disease advancement and poor survival." (PMID 38051374, 2024). "Our previous study tested the TNF levels after the NK cells were cocultured with prostate cancer cells at E/T ratio of 10:1 for 12 h, and we observed evident TNF-α secretion." (PMID 38245792, 2024). "Deacetylation of KLF5 in prostate cancer cells stimulated inflammatory cancer-associated fibroblasts (iCAFs) through TNF-α to release FGF9, which in turn activated FGFR1 signaling in prostate cancer cells." (PMID 38781024, 2024). "The results showed that the enriched signal pathways were mainly related to bacterial enteritis, including pathways in cancer, the PI3K-Akt and the TNF signaling pathway, MicroRNAs in cancer, pancreatic cancer, prostate cancer, and the MAPK signaling pathway." (PMID 37246319, 2024).
prostate carcinoma (continued). "Both the parental TBX19 and the TBX19‐202 peptides contribute to prostate cancer progression through molecular pathways such as DNA duplication, cell cycle, and TNF signaling." (PMID 39540264, 2024). "In several studies, resveratrol treatment blocked nuclear translocation of the p65 subunit of NF-κB in myeloid U-937 cells, in TNF-induced prostate cancer PC-3 cells, and in human CD34+ cells." (PMID 39458478, 2024). "These contradictory outcomes underscore the intricacy of TNF-α's role in the initiation and advancement of prostate cancer." (PMID 39554609, 2024). "The surprising discovery is in the prostate cancer group, the concentrations of the inflammatory cytokines IL-4, TNF-α, IL-1β, and IFN-α were significantly lower than those in the healthy control group (all p < 0.05)." (PMID 38833027, 2024). "We show that osteocytes suppress proliferative behavior in both breast and prostate cancer cells via secretion of soluble TNF‐α." (PMID 37967351, 2024). "IL‐8 has been associated with low‐third gastric cancer especially in the presence of cachexia, and has positively correlated with TNF‐α in a population of cachectic patients with advanced prostate cancer." (PMID 38481033, 2024). "It was determined that elevated serum levels of IL-8, TNF-α, and CCL2 are associated with accelerated progression to castration-resistant disease and correlate with poorer overall survival in prostate cancer patients." (PMID 39355131, 2024). "This study presents a novel cytokine mechanism, common to both breast and prostate cancer, whereby osteocytes can suppress cancer cell proliferation via TNF‐α secretion." (PMID 37967351, 2024). "In prostate cancer, metformin was reported to induce the suppression of pro-inflammatory cytokines IL-2, TNF-α, and INF-ɣ, which was correlated with the inhibition of the mTOR Pathway." (PMID 37842429, 2023). "MDK expression is induced by cytokines and growth factors such as TNF-α, which support prostate cancer cell survival." (PMID 37240085, 2023). "In prostate cancer cells, TNF-α was found to up-regulate the NF-κB pathway, thereby inducing the transcription of MDK." (PMID 37240085, 2023). "The result based on prostate cancer showed that mangiferin inverted TNF-α-induced mRNA as well as MMP-9 expression." (PMID 38137424, 2023). "RFK is essential for TNF-induced ROS production, which can influence the progress of breast invasive carcinoma and human prostate cancer." (PMID 37223030, 2023). "TNF-mediated NF-B/VEGFA axis is able to contribute to tumor angiogenesis, and autocrine HIF-1 and TNF increase the invasive potential of prostate cancer cells PC3 in a hypoxic tumor microenvironment." (PMID 37064125, 2023). "The stimulus of experimental cells with TNF-α enhanced the Matrix metallopeptidase 9 activity in prostate cancer cells." (PMID 38137424, 2023). "Another study also reported the absence of correlations between pretreatment and post-treatment serum concentrations of IL-4, IL-6, IL-10, and TNF-α, and fatigue symptoms in a group of 29 prostate cancer patients treated with radiotherapy." (PMID 36368974, 2022). "Another experiment was planned to observe the effect of fisetin on the tumor necrosis factor (TNF)-related apoptosis-inducing ligand-induced apoptosis potential in prostate cancer cells." (PMID 36558146, 2022). "TNF-α was also suggested to play an important role in the development of cachexia from prostate cancer patients." (PMID 36140220, 2022). "To determine if TNF signaling plays a role in the vascular events accompanying castration-induced regression of prostate cancer, we employed a subcutaneously implantable Myc-CaP tumor model." (PMID 36551505, 2022). "PEDF also downregulates CXCR4 and TNF, as well as increasing TNF-related apoptosis-inducing ligand to activate immunosurveillance in prostate cancer." (PMID 36555293, 2022).